TNF (tumor necrosis factor)
Diseases named in the same sentence as TNF in open-access papers (continued):
Sharing a sentence is not in itself a finding about the gene and the disease.
Stroke (continued). "The results also showed that there was a significant difference in the TNF-alpha rs1800629 G > A genotype distribution between stroke patients with normal and stroke patients with reduced HDL-C." (PMID 37240845, 2023). "The excess production of TNF alpha led to increased pain symptoms following these states, such as post-stroke pain." (PMID 37065345, 2023). "In a rat model of global stroke, a pinocembrin treatment administered daily for 7 days before a stroke decreased the infarct size and NF-κB, TNF-α, and IL-6 in the hippocampal tissue." (PMID 36901731, 2023). "TNF and IL-6 are potent, proinflammatory cytokines that significantly increase within the initial 24 hours following a stroke." (PMID 38313176, 2023). "TNF alpha is known to maintain cerebral homeostasis mainly but has been shown to increase in pathological states like infection or stroke." (PMID 37065345, 2023). "Further research is required to explore the effects of TNF alpha on stroke prognosis and determine the optimal frequency and duration of etanercept treatment for post-stroke pain." (PMID 37065345, 2023). "Regarding monocytes, classical CD14+/CD16- subtypes mainly secrete inflammatory TNF-α, IL-6 and IL-1β, and their blood number, as well as their expression of TLR-4, increase early after stroke, being independently associated with poor outcome in patients." (PMID 36674674, 2023). "Some animal stroke experiments have reported that lymphocytosis upregulates IL-10 levels and inhibits inflammatory cytokines such as IL-6 and TNF-α, thus exerting neuroprotective effects." (PMID 37616313, 2023). "In the same model, kaempferol administered for 7 days after stroke also decreased the NF-κB and pro-inflammatory cytokines such as IL-5, TNF-α, IL-1β, and IL-6, but the reduction of last three cytokines only occurred with high doses." (PMID 36901731, 2023). "The only previous report of cytokine measurement in CSF from dogs with naturally occurring stroke assessed for IL-2, IL-6, IL-8, and TNF." (PMID 37266378, 2023). "Macrophages, as the main cells of the peripheral immune system, have been proved to participate in the prognosis of stroke via secreting pro-inflammatory cytokines, such as TNF-α and IL-6, and anti-inflammatory cytokines, such as IL-10." (PMID 37199575, 2023). "Conversely, TNF-α production is triggered by ischemia during stroke as an inflammatory response, leading to the activation of MMP-9 expression related to secondary bleeding in the BBB." (PMID 37570794, 2023). "A previous investigation, however, highlighted the potential synergistically effects of TNF-α and IL-1β, considering their corresponding alleles together, on the risk of PSD at 2 weeks post-stroke." (PMID 36911716, 2023). "Clinically significant TNF-alpha rs1800629 G > A genotype distribution was found in both male and female stroke patients (p = 0.02)." (PMID 37240845, 2023). "Similar to what our findings showed, there was a significant correlation between the age of stroke patients and the TNF-alpha rs1800629 G > A genotypes (p 0.032)." (PMID 37240845, 2023). "Specific inflammatory blood markers correlate with outcomes after stroke, including proinflammatory cytokines like IL-1, IL-6, TNF, as well as anti-inflammatory cytokines like TGF and IL-10." (PMID 36691064, 2023). "Triglyceride and leptin levels as well as IFN-β, IFN-γ and TNF-α were elevated with higher BMI values, and the IL-6 concentration was reduced with higher BMI values after stroke in our data." (PMID 37587512, 2023). "The levels of TNF-a in CSF have been found to be increased in patients at 24 h, 1 week, and 2 weeks after stroke, and correlate with infarct volume and severity of neurological impairment." (PMID 37342100, 2023). "The neurotoxic and neuroprotective actions of TNF-α in the ischemic brain highlight the central role of TNF-α in the neuroimmune genesis of stroke." (PMID 36793730, 2023).
Stroke (continued). "In the early stage post-stroke, pro-inflammatory microglia can induce the destruction of gap junctions and increase the permeability of hemichannels by secreting TNF-α and IL-1β." (PMID 37464832, 2023). "Increased TNF-α concentrations are observed in peripheral blood of stroke patients 6–12 h after symptom onset." (PMID 36211352, 2022). "This review summarizes the latest research on TNF-α in stroke and explores its potential as a therapeutic target." (PMID 35265224, 2022). "Minutes to hours after stroke, the acute phase of stroke leads to production of pro-inflammatory cytokines, particularly IL-1β and TNF-α, which propagate the neuroinflammatory response through activation of danger signals." (PMID 35631536, 2022). "Although several studies have reported contrary results, the use of TNF-α as a marker of stroke remains promising." (PMID 35265224, 2022). "In parallel to the decrease in neuroinflammation mediated by A. borbonica polyphenols and caffeic acid in obese mice during stroke, the quantities of IL-6 and TNF-α were also lowered by polyphenols in the visceral adipose tissue of obese mice." (PMID 35624723, 2022). "The M1 phenotype is pro-inflammatory and secretes IL-6, tumor necrosis factor (TNF), and IL-1β, which contribute to brain injury after stroke." (PMID 36685518, 2022). "While IRF5 CKO led to a decrease only in IL-1β expression after stroke, IRF4 CKO caused up-regulation of both IL-1β and TNF-α in ischemic microglia." (PMID 35963621, 2022). "Given the role of methylation in reducing gene expression, it is logical that less methylation of the TNF-α promoter correlates with greater inflammation and stroke occurrence." (PMID 36361891, 2022). "There was also a decrease in the release of IL-1β and TNF-α from co-cultures involving monocytes from stroke patients (p < 0.05)." (PMID 36277912, 2022). "Following focal and generalized cerebral ischemia in animals and in cerebrospinal fluid, post-stroke patients demonstrated elevated concentrations of proinflammatory cytokines, IL-1 and tumor necrosis factor (TNF)." (PMID 35627746, 2022). "It is widely considered that TNF-α plays both a critical and initial role in the pathophysiology of stroke and provides both neurotoxic and neuroprotective effects." (PMID 35631536, 2022). "Because TNF-α ligand-receptor interactions are involved in almost every aspect of stroke-induced brain injury, it is a promising direction to use TNF-α as an inflammatory marker to predict the outcome of stroke." (PMID 35265224, 2022). "Several pro‐inflammatory mediators such as TNF‐α, IL‐1β, and IL‐6 have been proposed as key drivers of secondary vascular events after stroke." (PMID 35971650, 2022). "Of the pro-inflammatory mediators, TNF-α and IL-1β are considered to be the most hostile components in stroke brains, as well as blood-derived macrophages and resident microglia whose sources have been reported." (PMID 35968363, 2022). "Stroke induces an acute inflammatory response characterized by elevated levels of a series of cytokines such as IL-1β, IL-6, and TNF-α in the cerebrospinal fluid." (PMID 35467483, 2022). "It has been reported that compared to controls, IS patients have higher IL-6, IL-8, and TNFα protein in plasma and lower IL-6, IL-8, TNFα, IL-1α, and IL-1β mRNA in leukocytes within 72 h after stroke." (PMID 36547090, 2022). "TNF-α expression was not significantly elevated in the ischemic brain of DD/STZ mice at 1 day post-stroke; however, we observed the delayed increase in TNF-α in DD/STZ mice at 3days post-stroke." (PMID 35784349, 2022). "The TNF-signaling complex structure enables TNF-α to induce inflammation and cell death or to induce tolerance to ischemia after stroke." (PMID 35265224, 2022). "In researches done over the last few years, tumor necrosis factor-alpha (TNF-α) has emerged as a potential marker for stroke because of its essential role in stroke." (PMID 35265224, 2022).
Stroke (continued). "The cytokines TNF-α and IL-6 modulated infarct evolution in the experimental stroke and therefore received much attention as putative markers of stroke severity and neurological outcomes in humans." (PMID 36142524, 2022). "Strikingly, the transcription levels of multiple pro-inflammatory factors including TNF-α, IL-1β and IL-6 were significantly down-regulated and the anti-inflammatory factor IL-10 was significantly up-regulated in the stroke lesions of kaempferol-treated rats." (PMID 36293548, 2022). "Monocytes isolated from stroke patients or from rats following experimental stroke display reduced ability to produce the pro-inflammatory cytokines TNFα and IFNγ after stimulation with the bacterial endotoxin LPS." (PMID 38566903, 2022). "On the other hand, IFN-γ, IL-1β, and TNF-α showed reduced secretions in Mφ-MSC co-cultures involving stroke patient derived Mφ, as compared to healthy control derived Mφ." (PMID 36277912, 2022). "As early as 3 h post-stroke, microglia would polarize to an M1 predominant phenotype, exerting inflammatory actions and further contributing to brain injury by TNF-α, iNOS, and CD16/32." (PMID 35780249, 2022). "The exacerbated stroke outcomes in diabetic mice were accompanied by the upregulated expression of inflammatory factors (including IL-1β, TNF-α, IL-6, CCR2, and MCP-1) in the ischemic brain." (PMID 35784349, 2022). "The positive effects of treatment targeting TNF-α in stroke have been demonstrated in preclinical studies over the past few years." (PMID 35265224, 2022). "Numerous studies indicate that stroke lesion size positively correlates with measured IL-6 and TNF-α levels." (PMID 36567842, 2022). "In our study, the presence of the TNF-α-308 GG genotype and a higher serum concentration of TNF-α increases the likelihood of a stroke pathology." (PMID 35370618, 2022). "On the other hand, when TNF-α is used as a potential therapeutic target for stroke, blocking TNF-α can reduce focal ischemic injury and improve clinical outcomes." (PMID 35265224, 2022). "Statistical differences were also found between LACI and POCI for TNF-α assessed in <4.5 h and 1 day after the stroke." (PMID 36142524, 2022). "Previous time course studies have observed that TNF-α levels in monocytes derived from stroke patients peaks at around 72 h after stroke onset, and then decrease at day 7 after stroke onset." (PMID 36277912, 2022). "IL-1β and TNF-α play a key role in the neuroimmune development of stroke by promoting neurotoxicity and the development of harmful inflammation after cerebral ischemia." (PMID 35469165, 2022). "There are also conflicting reports of stroke-induced changes in TNF-α levels in serum and plasma due to its complex and pleiotropic signalling nature." (PMID 36142524, 2022). "In clinical settings, variations of histone acetylation (H3K9Ac) and methylation (H3K4me3) in stroke patients correlate with increased TNF-α concentrations as well." (PMID 36361891, 2022). "The high expression of serum miR-155, tyrosine protein kinase 2/STAT-3 and TNF-α in patients with AIS can trigger the inflammatory response after stroke, and miR-155 can be used as a potential inflammatory marker of AIS." (PMID 36275741, 2022). "At the same time, anti-TNF-α therapy can reduce brain damage in stroke, and it is also worth exploring as a therapeutic target." (PMID 35265224, 2022). "What’s more, focusing on effectively improving the development of neuroinflammation by regulation of TNF expression, is likely to find a way forward in repair and recovery after stroke." (PMID 36389810, 2022). "Key cytokines related to inflammation in stroke are tumor necrosis factor-α (TNF-α), interleukin (IL)-1, IL-6 and IL-10." (PMID 35631536, 2022). "Some animal stroke experiments have suggested that increased lymphocytes up-regulate the levels of IL-10 and inhibit the inflammatory cytokines such as IL-6 and TNF-α, thus playing a neuroprotective role." (PMID 35370926, 2022).
Stroke (continued). "In this case‒control study, serum periostin and TNF-α levels were measured using ELISA, and patients were scored on the National Institutes of Health Stroke Scale (NIHSS) and modified Rankin Scale (mRS)." (PMID 36127647, 2022). "The number of Th1 and Th17 cells increases within the first week after stroke, accompanied by an increase in the proinflammatory cytokines, including TNF-α, IL-1, IL-2, IL-12, and IL-17, thereby exacerbating the neurological damage." (PMID 36186129, 2022). "Stroke triggered peripheral inflammatory responses, indicated by the elevated levels of circulating IL-1β and TNF-α, which were lowered by HSYA and NAC." (PMID 35453413, 2022). "Our data indicated that TNF-α significantly decreased in the 60 Hz cell/PEMF group (10 MT for 30 min) after cell transplantation in the mouse stroke model." (PMID 35163096, 2022). "Their activation and recruitment at the site of infarction always coincide with the maximum synthesis of proinflammatory mediators (such as TNF-α and IL-6) and associated biomarkers (such as CRP), which result in neuronal damage after stroke." (PMID 35978885, 2022). "In general, cytokines such as TNF-α activation can be detected early in a few hours after stroke, even before significant neuronal death has occurred, and the spleen secretes large amounts of TNF-α into circulating blood at the hyper-acute stage." (PMID 36064468, 2022). "It has also been reported that the proliferation of progenitor cells was suppressed via TNF‐α secretion by activated microglia after stroke." (PMID 35715988, 2022). "In animal models of acute stroke, GLP-1RA reduce TNF and IL-6 levels, both pro-inflammatory cytokines involved in stroke pathology." (PMID 36636739, 2022). "In summary, TNF-α promotes platelet invasion and aggregation in the ischemic cortex, which aggravates symptoms of stroke." (PMID 35781632, 2022). "We also predict that future research will be directed at how to better treat stroke in PSN by effectively balancing the biphasic effects of TNF." (PMID 36389810, 2022). "There was also a statistically significant decrease in the release of IL-6, IL-1β, and TNF-α from trans-well co-cultures of MSCs with stroke derived monocytes as compared to co-cultures using healthy monocytes (p < 0.05)." (PMID 36277912, 2022). "This is an unfortunate situation, since TNFα plays a pro-inflammatory role in both acute brain disease, such as stroke, and chronic brain disease, such as AD and PD." (PMID 35745855, 2022). "Additional support for reduced levels of TNF-α, and IL-6, in addition to IL-1β, comes from studies of chronic metformin pre-treatment in a rodent model of adult stroke." (PMID 35705953, 2022). "Studies have reported that various molecules secreted by glial cells, such as TNF-α, thrombospondin, hevin have the ability to repair synaptic dysfunction after stroke." (PMID 35281064, 2022). "Administration of L-4F to db/db T2DM stroke mice mitigated macrophage infiltration and reduced TNFα in the ischemic brain." (PMID 35572941, 2022). "In this study, a higher concentration of inflammatory biomarkers IL-6, and TNF-α within 4.5, 24 h and 7 days after the onset of stroke was observed compared to healthy participants who acted as a control group." (PMID 36142524, 2022). "It has been shown that the increase in TNF-α concentration within 24 and 48 h after stroke, and the observed slow decrease occurring within 72 and 144 h after stroke, correlates with clinical improvement in patients in the acute phase of ischemic stroke." (PMID 36142524, 2022). "Elevated TNF-α has similarly been reported in stroke patients as early as 6–12 h post-symptom onset, rising between 24 and 48 h and gradually declining from 72–144 h." (PMID 35631536, 2022). "Serum concentration of IL-6 and TNF-α of the subgroups of stroke patients with a favourable and an unfavourable outcome after IV thrombolysis at admission, discharge, after 3 months, and after 1 year." (PMID 36142524, 2022).
Stroke (continued). "The present study assessed the effects of two types of selected aerobic exercises prior to stroke induction and characterized the expression of TrkB, TNF-α, and MMP2 genes in vivo." (PMID 33954182, 2021). "TNF is known to have both beneficial and deleterious effects in stroke, whereas IL-1Ra selectively antagonizes the deleterious effect of IL-1." (PMID 33924148, 2021). "The concentration (↑68%) and specific amount (↑147%) of TNF-α were significantly higher in patients with stroke than in control." (PMID 34433866, 2021). "HSCT has been used in patients with a severe phenotype that did not respond to medical treatments such as tumor necrosis factor (TNF) inhibitors, which represent the best option in controlling fever episodes and vasculopathy and in preventing stroke." (PMID 34721429, 2021). "The pleiotropic cytokine tumor necrosis factor (TNF) is one of the most well-studied cytokines in relation to stroke and neuroinflammation, and it demonstrates both beneficial and detrimental effects." (PMID 33918875, 2021). "We tried focusing on the preparation of nano formulation by thin-film hydration method and its characterization, then after inducing stroke, levels of inflammation and oxidative factors (TNF-α, IL-1ß, MDA) were measured in brain tissue." (PMID 34600570, 2021). "Salivary TNF-α differentiates (with high sensitivity and specificity) stroke patients with normal cognitive function from patients with mild to moderate cognitive decline." (PMID 34433866, 2021). "M1 type microglia accelerate the polarization of Th1 cells by the secretion of IL-12 and TNF-α in the early stages of stroke." (PMID 34248961, 2021). "Local inflammation induced by TNF has also been suggested to mobilize endogenous bone marrow (BM) cells to the site of injury, and it is known that TNF is upregulated in the ischemic penumbra early after stroke onset." (PMID 33924148, 2021). "In stroke patients, those with high TNF-α levels and with hyperglycema develop greater neurological deficits and the outcome is worse." (PMID 34073455, 2021). "TNF-α also participates in ROS production and promotes formation of infarct area in stroke pathogenesis." (PMID 34381129, 2021). "IL1B, IL10, TNF, IL6, and ICAM1 are closely related to the inflammatory response after stroke, among which IL-10 is an important anti-inflammatory factor, while L1B, TNF, and IL6 are proinflammatory factors." (PMID 33727944, 2021). "Proinflammation cytokines, such as IL-6, IL-10, and TNF-α, have been shown to be elevated in the rat models of stroke that were subjected to a pretreatment of RIC." (PMID 34439830, 2021). "Immediate early gene products activate transcription sites on the cytokine genes such as tumor necrosis factor-α (TNF-α) or interleukin-1β (IL-1β) that appear within hours after stroke." (PMID 34439764, 2021). "For example, in mouse ischemic stroke models, lymphocytes infiltrating into the whole stroke brain were complicated with inflammatory cytokines IL-1α, IL-1β, IFN-γ, TNF-α, and IL-6 at 2 weeks after stroke." (PMID 34421544, 2021). "Of particular note is the evaluation of TNF-α and IL-6, whose serum levels increase in the acute phase of stroke as well as correlate with its cerebrospinal fluid (CSF) levels and stroke focus size." (PMID 34433866, 2021). "Anti-TNF agents are the currently preferred treatment based on the positive effect, in particular, in preventing stroke." (PMID 33757531, 2021). "The protein expressions of TNF-α, caspase-3, and cleaved caspase-3 in the stroke 1-day group were stronger than those in the sham 1-day group (n = 7, p < 0.001)." (PMID 33642941, 2021). "The cytokines IL-1β and TNF-α play an important role in regulating immune responses after ischemic stroke and are stroke potential therapeutic targets." (PMID 34898370, 2021). "Our study is the first to demonstrate that salivary TNF-α can be a potential biomarker of stroke patient’s functioning." (PMID 34433866, 2021).